ERBB2 (erb-b2 receptor tyrosine kinase 2)
Diseases named in the same sentence as ERBB2 in open-access papers (continued):
Sharing a sentence is not in itself a finding about the gene and the disease.
breast cancer (continued). "According to the status of the hormone receptors (ER and PR) and HER2 (ERBB2), breast cancer is categorized into four primary subtypes: Lumina-A, Lumina-B, HER2 positive, and triple negative breast cancer (TNBC), each subtype has a matching treatment." (PMID 36353118, 2022). "Approximately 15–20% breast cancer patients demonstrate the amplification and/or overexpression of human epidermal growth factor receptor 2 (ErbB2)." (PMID 35501821, 2022). "The study found that, in patients with pretreated ERBB2-positive advanced breast cancer, despite acceptable safety and significant clinical benefits, margetuximab plus chemotherapy exhibited unfavorable cost-effective result over trastuzumab plus chemotherapy." (PMID 36159262, 2022). "Many reports explained the anticancer properties of melatonin in ERBB2, particularly in breast cancer." (PMID 35937803, 2022). "Whereas, the level of ERBB2d16 relative to that of ERBB2 varied substantially, as previously reported in breast cancer specimens." (PMID 35463314, 2022). "An in vitro analysis revealed that ErbB2-CAR-NK-92 cells successfully eradicated ErbB2 + breast cancer cells." (PMID 36153626, 2022). "In our previous study, we explore the potentials of reexpressing PTPRO by using 5-azacytidine in ERBB2-positive breast cancer cells." (PMID 35431974, 2022). "Although ERBB2 fusions were rare, they occurred more frequently in gastroesophageal junction cancer (3.12%), breast cancer (1.89%), and urothelial carcinoma (1.72%)." (PMID 36276102, 2022). "The treatment options for breast cancer are commonly dependent on the presence of tumor, lymph node involvement, metastasis, staging, histological grade, hormone receptor status, ERBB2 (formerly HER2 or HER2/neu) overexpression, and menopausal status." (PMID 35888054, 2022). "Amplification of ERBB2 or overexpression of the HER2 protein product has been reported in 18%-20% of breast cancers." (PMID 35849877, 2022). "Based on the tumor size and Human epidermal growth factor receptor-2 (HER2/erbB-2) expression status, patients with ERα-positive breast cancer are initially considered for endocrine therapy to reduce the risk of malignancy and tumor recurrence after treatment." (PMID 35453496, 2022). "The role of ERBB2 in cancer progression is well established and targeting ERBB2 through specific monoclonal antibodies, such as trastuzumab and pertuzumab, represents the gold standard to treat HER2-positive breast cancer patients in clinics." (PMID 35406375, 2022). "The coverage of all ERBB2 exons in the tumor sample with fusion was within the 95% CI of the exon coverage in breast cancer samples, as well as above the 95th percentile exon coverage of normal breast tissue samples (data not shown)." (PMID 36009413, 2022). "For instance, the EGF Receptor (EGFR) is commonly overexpressed in head or neck cancer cells, and ErbB-2/HER2 is overexpressed in breast cancer cells." (PMID 35158804, 2022). "ERBB2 gene amplification or HER2 overexpression is prevalent in approximately 20% of breast cancers, and heterogeneity also exists within this subtype." (PMID 36091103, 2022). "Black women had the highest incidence of less favorable breast cancer subtypes, including triple-negative (12.2 per 100 000 person-years), lumina B (6.8 per 100 000 person-years), and ERBB2 (previously HER2 or HER2/neu) enriched (3.4 per 100 000 person-years)." (PMID 35699957, 2022). "It is administered to previously treated ErbB2-positive metastatic breast cancer patients and received FDA approval in 2019." (PMID 36235168, 2022). "Downregulation of p38γ using shRNA in breast cancer cells overexpressing ErbB2 decrease the alcohol-induced increase in CSCs, mammosphere formation, and migration and invasion." (PMID 35501462, 2022).
breast cancer (continued). "Third, ligand-mediated activation of ERBB3 has been shown to result in PI3K/AKT-mediated resistance to TKIs in a variety of cancers, including ERBB2-amplified breast cancer cells stimulated with ERBB3 ligands, NRG1 or HRG." (PMID 34675407, 2022). "In ErbB2-induced mammary tumorigenesis, Ink4a/Arf+/− mice showed decreased p16INK4a, increased Ki-67 expression, increased cyclin D1 protein but decreased mammary tumor apoptosis." (PMID 36358806, 2022). "d16-HER2 is a splice variant derived from exon 16 skipping in ERBB2, and is expressed in many HER2-positive mammary tumors." (PMID 36276152, 2022). "ERBB2 tyrosine kinase, also known as HER2/Neu, and amplified in breast cancers, has been described to associate with rDNA and to increase rRNA synthesis." (PMID 36497261, 2022). "The SOPHIA trial demonstrated a head-to-head advantage of margetuximab compared to trastuzumab, providing a promising option for patients with pretreated ERBB2-positive advanced breast cancer in later line treatment." (PMID 36159262, 2022). "Beyond single nucleotide variants, the ERBB2 gene locus is amplified and a diagnostic marker in several entities, including HER2-positive breast cancer." (PMID 35625984, 2022). "Eligible patients were diagnosed with ERBB2-positive breast cancer (primary tumor size >2 cm or pathologically confirmed lymph node–positive cancer, without distant metastases) with a clinical stage of II or III." (PMID 35797012, 2022). "This study suggests a possible role of PD-L1 expression in patient selection for novel deintensified immunotherapy combination in ERBB2-positive early breast cancer in the future." (PMID 35797012, 2022). "Therapeutics targeting ERBB receptors in breast cancer include the humanized anti-ErbB2 antibody trastuzumab (Herceptin) and the tyrosine kinase inhibitor, lapatinib which are efficacious and widely used in the clinic." (PMID 35846378, 2022). "We found previously that ErbB2 blocks breast cancer cell anoikis by downregulating transcription factor IRF6." (PMID 35933456, 2022). "A candidate promoter for breast cancer is Erb-B2 receptor tyrosine kinase 2 (ERBB2) gene promoter; however, this is expressed in only 20–25% of tumors, and it is also active in prostate, pancreas, colon, and ovary cancer cells." (PMID 36145609, 2022). "Two major targets in breast cancer genesis are estrogen receptor α (ERα) and epidermal growth factor 2 (HER2/ERBB2)." (PMID 36421127, 2022). "A large segment (25–30%) of human breast cancers overexpress the protooncogene c-neu/c-erbB-2, which codes for the HER2 cell surface protein." (PMID 35742818, 2022). "Trastuzumab is only effective for the treatment of ERBB2-overexpressing tumors, which are a minority of breast cancer cases." (PMID 35888054, 2022). "Compared with ERBB2 wild-type tumors, ERBB2ΔEx16+ mammary tumors exhibit a higher degree of intratumoral heterogeneity as shown by distinct signaling and gene expression profiles associated with the activation of tumor initiation and progression." (PMID 36686783, 2022). "Univariate and multivariate Cox proportional hazards model predicting survival in ERBB2-positive breast cancer patients." (PMID 35431974, 2022). "Trastuzumab, the main treatment for human epidermal growth factor receptor 2 (HER2/ErbB-2)-positive breast cancer, has been proposed to be mechanistically dependent on the release of type I and type II IFNs." (PMID 35292881, 2022). "Multiplexed QASeq improves LoD to allow confident distinguishing 2.05 ploidy from normal 2.00 ploidy, and is applied to longitudinal serial 57 plasma cfDNA samples from patients with metastatic ERBB2+ (HER2+) breast cancer." (PMID 35379811, 2022). "About 20% of breast cancers have amplifications in HER2 (ERBB2), a member of the EGFR family of RTKs, and this correlates with a more aggressive disease." (PMID 35832792, 2022). "For example, ErbB-2/HER2 is commonly overexpressed in 40% of ductal carcinoma in situ (DCIS) breast cancer cases." (PMID 35158804, 2022).
breast cancer (continued). "The fact that Dsg1 binds to Erbin, which stabilizes ErbB2 in breast cancer cells, raises the possibility that Erbin stabilizes ErbB2 in the proximity of Dsg1 in the superficial epidermis." (PMID 35686051, 2022). "We found that ErbB2 downregulates IRF6 in breast cancer cells by activating a protein kinase MEK and its target protein kinase ERK." (PMID 35933456, 2022). "Of note, a higher expression of the mRNA levels of CXCR1/2 was found in basal breast cancer subtype in relation to the luminal A, luminal B, ERBB2 and normal-like molecular subgroups." (PMID 35954247, 2022). "We selected breast cancer in order to compare HER2/ERBB2 activity with clinical diagnosis of HER2-overexpression." (PMID 35879309, 2022). "Human epidermal growth factor receptor 2 (HER2/ERBB2) positive breast cancer accounts for 20–25% of all breast cancers." (PMID 36059813, 2022). "Despite the availability of all these molecular data also for breast cancer, only a few studies have filtered patients according to the presence of BRCA1/2 mutations or the amplification/overexpression of ErbB2." (PMID 35740092, 2022). "The role of ERBB2d16 played in promoting EMT has been reported in breast cancer, and in the prior studies, the number of mesenchymal cells was significantly increased in high ERBB2d16 tumor tissues compared with high ERBB2 breast tumor tissues." (PMID 35463314, 2022). "Lapatinib is one of tyrosine kinase inhibitors targeting epidermal growth factor receptor (EGFR/ErbB1) as well as HER2/ErbB2 specifically for treating HER2+ subtypes of breast cancer." (PMID 36936274, 2022). "In ductal breast carcinoma, the 1p36 deletion is associated with grade, ERBB2 loss, and loss of BCL2 expression and is known to be a common feature underlying breast cancer development and the carcinogenesis of various cancer types." (PMID 35992833, 2022). "Among the tumors, 0.28% harbored ERBB2 fusions, which occurred more commonly in gastroesophageal junction cancer (3.12%; 3/96), breast cancer (1.89%; 8/422), urothelial carcinoma (1.72%; 1/58), and gastric cancer (1.60%; 23/1,437)." (PMID 36276102, 2022). "The oncogenic role of ERBB2 has been poorly investigated in basal-like/triple-negative breast cancers owing to the low expression of this receptor in these breast cancer subtypes." (PMID 35406375, 2022). "Since PTPRO expression is closely related to ERBB2 status, we thus further investigated the relationship between PTPRO expression and clinical outcomes in ERBB2-stratified breast cancer patients in a large dataset." (PMID 35431974, 2022). "Breast cancer expressing ERBB2/HER2 are classified as HER2+, independently from the expression of ER and/or PR." (PMID 35406375, 2022). "lncRNA AFAP1-AS1 interacts with HNRNPD, promotes the translation of ERBB2, and induces drug resistance in breast cancer." (PMID 36127734, 2022). "Lapatinib is a tyrosine kinase inhibitor (TKI) targeting the epidermal growth factor receptors ErbB1 and ErbB2, also known as HER2, which is approved for use in HER2 positive breast cancer." (PMID 36013562, 2022). "Appropriate therapeutic measures are taken based on different breast cancer subtypes, such as HR+/ERBB2− (seven-tenths of the total), ERBB2+ (one-fifth of the total) as well as triple-negative (one-tenth of the total)." (PMID 36936274, 2022). "Functional oncogenic links between ErbB2 and ERRα in HER2+ breast cancer patients support a therapeutic benefit of co-targeted therapies." (PMID 36097051, 2022). "At the same time, since ERBB2 amplification mainly occurs in gastric cancer, colorectal cancer, and breast cancer, we focused on these cancer types in our work." (PMID 36276102, 2022). "ERBB2 (HER2) is overexpressed in 15-20% of breast cancer in response to EGF activation, and plays a major role in EMT." (PMID 36034422, 2022). "In breast cancer cells, CHK has been shown to be associated with ErbB-2 (via CHK SH2 domain) upon heregulin stimulation." (PMID 36568988, 2022).
breast cancer (continued). "The mechanism of abnormal activation of the PAM pathways in breast cancer includes variations in key molecules, such as amplification or overexpression of RTKs (e.g., HER2/ERBB2) and KRAS (kirsten rat sarcoma viral oncogene) mutation." (PMID 36010585, 2022). "IHC is a well-established method to allow subtyping of breast cancer in the clinical setting (luminal A, luminal B, ERBB2-overexpression, and basal-like) according to gene expression models, by using a four-marker panel (ER, PR, HER2, and Ki-67)." (PMID 35887192, 2022). "Our results pave the way towards the development of novel anticancer strategies for basal-like breast cancer patients based on the interception of the NRG1/ERBB3/ERBB2 signaling axis." (PMID 35406375, 2022). "The Her2 (ERBB2) receptor tyrosine kinase is amplified in 15–20% of breast cancers, and historically has correlated with poor prognosis." (PMID 36480552, 2022). "It is widely known that ERBB2 can be activated by overexpression, amplification, or alteration in multiple cancers, for instance, breast cancer, bladder cancer, and lung cancer, which has also been identified in patients with BTC." (PMID 36072793, 2022). "For breast cancer, human epidermal growth factor receptor 2 (HER2)/ErbB-2 gene amplification or protein overexpression is associated with poor survival." (PMID 35287613, 2022). "Trastuzumab has been recommended and widely used for selected group of breast cancer patients who have amplification of ErbB2/Her2 (Her2-positive)." (PMID 36498915, 2022). "It captured pathways related to resistance such as “mechanisms of resistance to EGFR inhibitors in lung cancer” and “Anti-apoptotic action of ErbB2 in breast cancer”." (PMID 35351890, 2022). "ERBB2-KD fusions occurred more commonly in gastroesophageal junction cancer (3.12%; 3/96), urothelial carcinoma (1.72%; 1/58), breast cancer (1.42%; 6/422), and gastric cancer (0.83%; 12/1,437)." (PMID 36276102, 2022). "Lapatinib is a potent double tyrosine kinase inhibitor of the epidermal growth factor receptor (EGFR) and HER-2 which inhibits the proliferation of breast cancer cells with overexpression of ErbB2 and EGFR." (PMID 36467032, 2022). "One of the most impactful biologics for the treatment of breast cancer is the humanized monoclonal antibody, trastuzumab, which specifically recognizes the HER2/neu (HER2) protein encoded by the ERBB2 gene." (PMID 36291900, 2022). "Increased PKCδ mRNA is correlated with diminished survival in ErbB2-positive breast cancer as well as estrogen receptor-positive breast cancer." (PMID 35588786, 2022). "Breast cancer cells that have been exposed to ErbB2 overexpression were resistant to 5-fluorouracil." (PMID 36144783, 2022). "It was approved in 2013 by the FDA after the impressive results of two Phase III trials in patients with ErbB2-positive advanced breast cancer." (PMID 36235168, 2022). "Recently, a microfluidic chip-based exosomal mRNA sensor was developed to directly detect exosomal ERBB2 in blood for the diagnosis of HER2-positive breast cancer." (PMID 36430471, 2022). "Two breast cancer patients and two colorectal cancer patients had 2 different ERBB2-KD fusions each, and 1 colorectal cancer patient had 3 different ERBB2-KD fusions." (PMID 36276102, 2022). "HER2 gene (ERBB2) amplification and/or HER2 protein overexpression is detected in approximately 15–20% of breast cancers and is associated with more aggressive disease, progression, metastasis, and poor prognosis." (PMID 34998412, 2022). "Based on the different molecular classifications, breast cancer can be divided into three subtypes: hormone receptor-positive/ERBB2-negative, ERBB2-positive, and triple-negative breast cancer (TNBC)." (PMID 35600860, 2022). "Around 20 to 30% of women with breast cancer diagnoses have overexpressed Human epidermal growth factor receptor 2 (ERBB2, formerly HER2), which is associated with more aggressiveness and worse prognosis." (PMID 36159262, 2022).
breast cancer (continued). "Our findings suggest that PTPRO is not only able to serve as an independent prognostic indicator, but upregulating PTPRO can also reverse the lapatinib resistance of ERBB2-positive breast cancer." (PMID 35431974, 2022). "Our retrospective study showed ERBB2 CNG in breast cancer cases has a high PPV for HER2-positivity by IHC/FISH by ASCO/CAP 2018 guidelines (PPV for tissue NGS 97%, ctDNA 93%)." (PMID 35126865, 2022). "We thus suggest the administration of neuregulin 4 as a strategy to improve the efficacy of anti-ERBB2 neutralizing antibodies in breast cancer patients." (PMID 35664762, 2022). "One breast cancer patient had 2 different ERBB2-KD fusions, and the remaining 21 patients had 1 ERBB2-KD fusion." (PMID 36276102, 2022). "Studies have suggested that the ERBB2 mutations play an important role in the pathogenesis, development, and resistance to anti-HER2-targeted breast cancer drugs." (PMID 36276102, 2022). "ERBB2-positive, low expression has recently gained interest due to recent encouraging published results in breast cancer." (PMID 35954382, 2022). "We found that 1) reduced levels of PTPRO correlate with poorer clinical outcomes; and 2) overexpressed PTPRO in lapatinib resistant ERBB2-positive breast cancer cells is capable of reversing lapatinib-resistance." (PMID 35431974, 2022). "The estrogen receptor (ER) and HER2 (c‐erbB2, HER2/neu) signaling pathways are the dominant drivers of cell proliferation and survival in the majority (85%) of breast cancer cases." (PMID 35945910, 2022). "The ErbB2 gene codifies for a tyrosine kinase receptor and is well known for its critical role in breast cancer progression and acute lymphoid leukemia." (PMID 36292100, 2022). "In tumor cells, LOXL2 can upregulate human epidermal growth factor receptor 2 (ErbB2) expression through the production of reactive oxygen species (ROS), and ErbB2-positive breast cancer patients with high LOXL2 expression have poorer OS and MFS." (PMID 36293126, 2022). "Tumours that overexpress the ERBB2 gene–around 15–30% of human breast cancers—are typically aggressive and difficult to treat." (PMID 36454979, 2022). "A significant proportion of breast cancers are driven by ErbB2/Her2 oncoprotein that they overexpress." (PMID 35933456, 2022). "Breast cancers which lack the expression of estrogen receptor (ER), progesterone receptor (PR), and amplification or overexpression of ERBB2 (HER2) are classified as triple-negative breast cancer (TNBC)." (PMID 35444182, 2022). "We also observed that a small molecule proteasome inhibitor bortezomib used for multiple myeloma treatment upregulates IRF6 and BLNK in detached ErbB2-positive breast cancer cells and kills them in a BLNK-dependent manner." (PMID 35933456, 2022). "HER2DX is a prognostic and predictive assay in early-stage HER2-positive breast cancer based on clinical features and the expression of 4 gene signatures (immune, proliferation, luminal differentiation and HER2 amplicon), including ERBB2 mRNA levels." (PMID 36374768, 2022). "ERBB2 amplifications fell most frequently in breast cancer (80/503, 15.9%), stomach cancer (83/998, 8.3%), biliary tract cancer (57/840, 6.8%), intestine cancer (8/179, 4.5%), and esophagus cancer (7/195, 3.6%)." (PMID 35911441, 2022). "Glycolytic inhibitors combined with chemotherapy overcome resistance and lead to more potent inhibition of glycolysis in ErbB2-positive breast cancer." (PMID 36059650, 2022). "We next assessed the impact of PTPRO on the lapatinib resistance in ERBB2-positive breast cancer cells." (PMID 35431974, 2022). "The consensus “HER2 amplicon” in breast cancers located at the 17q12–21 chromosomal region contains (besides ERBB2) at least five other genes (STARD3, TCAP, PNMT, PGAP3, and MIEN1)." (PMID 36139701, 2022).